INS (insulin)
Diseases named in the same sentence as INS in open-access papers (continued):
Sharing a sentence is not in itself a finding about the gene and the disease.
diabetes (continued). "Diabetes mellitus (DM) is a chronic metabolic disorder of various origins that occurs when the pancreas fails to produce insulin in sufficient quantities or when the organism fails to respond to this hormone in an efficient manner." (PMID 27546348, 2017). "The PLCO study did not collect type of diabetes (type 1 vs. type 2) or information on insulin dependence and other treatments." (PMID 28753646, 2017). "Type 2 Diabetes (T2D) starts with hyperinsulinemia, but this condition deteriorates during the progression of diabetes until the patients can no longer produce insulin." (PMID 28070499, 2017). "An insulin deficit in an organism or a lack of cell response to the produced hormone leads to diabetes mellitus." (PMID 28296883, 2017). "For example, C57BL6/SJL mice with the RIP-IFNβ transgene do not develop overt diabetes, but display mild hyperglycemia with decreased glucose-stimulated INS secretion and impaired glucose tolerance characteristic of a pre-diabetic state." (PMID 28959234, 2017). "Subjects with Type 2 diabetes accounted for 96% total population with diabetes, and more than 75% of them were not on insulin therapy." (PMID 29070034, 2017). "A mouse knockout of Siglec-F was nevertheless subjected to functional in vivo studies, but showed no visible effect on insulin secretion and diabetes progression." (PMID 28378743, 2017). "All these studies concluded that epigenenetic changes were a function of hyperglycemia and reduced insulin production in STZ-induced diabetes and not by STZ treatment alone." (PMID 28694462, 2017). "In this study, we demonstrate that, with the experimental set-up described, insulin+, MAFA+, NKX6.1+ S7 cells can be generated in vitro from hiPSCs regardless of HNF4A mutation carrier status or diabetes status." (PMID 28684784, 2017). "Therefore, combination therapy such as PDE5i, insulin and statin, etc. should be the preferred treatment strategy for DMED, especially in the setting of severe diabetes." (PMID 28245261, 2017). "NEUROG3 also displays efficacy in trans-differentiating hepatic cells into insulin-secreting cells which show a rapid but not sustained diabetes-reversal effect." (PMID 29096722, 2017). "Hemochromatosis patients with neither diabetes nor cirrhosis had normal insulin sensitivity but their acute insulin responses to glucose were decreased." (PMID 28331855, 2017). "Although sedentary activity data was available, data on diabetes in 11 year was unavailable as insulin or blood glucose values are not usually measured in this age group." (PMID 28355278, 2017). "A majority (59.5%) of the patients were on oral anti diabetic agents (OAD) alone, followed by 22.2% on combination therapy of OAD plus insulin, 10.8% on insulin alone and 7.6% of the participants were not on any pharmacotherapy for diabetes." (PMID 28583113, 2017). "Unlike our initial assessment, we then judged him to have diabetes mellitus with preserved insulin secretion from the pancreas, and he was prescribed glimepiride 1 mg once daily." (PMID 28610599, 2017). "Diabetes mellitus is a chronic metaolic disease characterized by hyperglycemia resulting from absolute or relative lack of insulin or insulin insensitivity." (PMID 29844778, 2017). "IR is not unique to those with T2D, as patients with T1D tend to be more insulin resistant than their counterparts without diabetes." (PMID 28836234, 2017). "Moreover, all the metabolic indicators including TC, TG, FFA, GLU, insulin, HOMAIR, HOMAIS, leptin, HbA1C, HDL, LDL, and TNF were previously proved to have the relationship with chronic disease of hypertension, diabetes mellitus, and cardiovascular disease." (PMID 28115972, 2017). "It is notable in the present study that patients receiving statins were older, and had longer duration of diabetes and insulin treatment compared to non-users." (PMID 28830436, 2017).
diabetes (continued). "The effect of magnesium on insulin metabolism and glycaemic control, in both patients with diabetes and without diabetes, has been studied in several randomised clinical trials." (PMID 28224192, 2017). "IRS1 is an important factor in insulin-signaling pathways while GLUT-4 is the major glucose transporter in skeletal muscle, adipose tissues and liver and, hence, both are therapeutic targets in the management of diabetes." (PMID 29137205, 2017). "FGF21 stimulates insulin secretion in ex vivo islets isolated from rodent models of diabetes, but does not affect insulin secretion from islets isolated from healthy mice." (PMID 28770320, 2017). "Nevertheless, more studies on the complex relationship between the endocytic machinery components and diabetes features, such as hyperglycemia, lack of insulin, and albumin overload, are indeed necessary." (PMID 28676554, 2017). "Type 2 diabetes mellitus, formerly known as non-IDDM, is caused by a combination of inadequate insulin secretion and insulin resistance." (PMID 29209211, 2017). "Type 2 diabetes mellitus (T2DM) is a progressive condition in which the body becomes resistant to the normal effects of insulin and/or gradually loses the capacity to produce enough insulin in the pancreas." (PMID 29295509, 2017). "Insulin treatment was shown to be protective against the annual decline of SMI (standardized β 0.195; p = 0.025) even after adjusting for covariates, including age, gender, duration of diabetes, and body mass index." (PMID 28246927, 2017). "Here, we compared diabetic patients taking metformin versus those taking insulin plus metformin or no diabetes medication as well as non-diabetic subjects." (PMID 28947922, 2017). "This study provides important information for the development of nonpharmacological strategies for the treatment of diabetes mellitus, particularly in diabetic individuals that depend on exogenous insulin." (PMID 28536139, 2017). "Diabetes and diabetes with insulin did not have a significant difference in glucose (p-value = 0.2689)." (PMID 29121074, 2017). "Crude and adjusted odds ratios for breast cancer clinicopathological subtypes of women with diabetes treated with or without insulin compared to women without diabetes in subgroups of menopausal status using (multinomial) logistic regression." (PMID 28076434, 2017). "Chemotaxis of monocytes is also impaired in patients with diabetes, a defect which does not improve with insulin." (PMID 29270319, 2017). "The second patient was readmitted for hyperglycaemia, who also did not have their insulin dose change explicitly communicated on their last discharge summary from a diabetes and endocrine ward." (PMID 28852529, 2017). "We propose a novel mechanism by which insulin (INS) resistance might arise in both type 1 (T1DM) and type 2 (T2DM) diabetes: Rapid glycation of the insulin receptor (IR) may result in decreased INS binding and subsequent impairment of IR activity." (PMID 29207492, 2017). "Three patients without diabetes with recurrent spontaneous hyperinsulinaemic hypoglycaemia and ‘positive’ insulin antibodies." (PMID 27588366, 2017). "Second, physical activity can reduce blood glucose and increase insulin sensitivity in people with and without diabetes directly." (PMID 28367452, 2017). "Nevertheless, glucose and insulin dynamics are complicated, nonstationary, nonlinear, and individual-dependent, making self-management of diabetes a complex task." (PMID 28448498, 2017). "DPP-4is is a new class of anti-diabetes which can prevent the rapid degradation of glucose-dependent insulinotropic polypeptide (GIP) and glucagon-like peptide 1(GLP-1) through inhibition of DPP-4, thus enhancing insulin secretion." (PMID 29206832, 2017). "Subjects who just received metformin presented lower methylation levels, mainly in the promoter region, in all three transporter genes compared to those participants who were taking insulin plus metformin or no diabetes medication." (PMID 28947922, 2017).
diabetes (continued). "Indeed, the loss of insulin secretion due to the loss of function of TCF7L2 in the pancreatic islet and polymorphisms of the human TCF7L2 allele further indicate that the susceptibility and pathogenesis of diabetes mellitus may be caused by disturbance of the Wnt signaling pathway." (PMID 28303247, 2017). "The NDF25 and NDF35 groups with 75.7% and 64.4% serum insulin respectively presented relative normoglycemia, whereas the FDF35 (85.8% serum insulin) were notably hyperglycaemia (>300 mg/dL) throughout the 6weeks post diabetes confirmation." (PMID 28129400, 2017). "The non-insulin users were treated with non-insulin antidiabetic drugs (35%) or diabetes was controlled by diet and exercise only (40%)." (PMID 28076434, 2017). "In contrast, average fasting insulin concentrations were stable during observation in the three groups that did not develop diabetes, even though the trajectories of fasting insulin were substantially distinct (all P < 0.001)." (PMID 28266592, 2017). "The insulin-treated patients exhibited significantly higher levels of SBP and urinary ACR, a longer duration of diabetes, higher prevalence of diabetic retinopathy, and lower levels of grip strength, triglycerides, AST, ALT, and eGFR than the non-insulin-treated patients." (PMID 28246927, 2017). "Of note, there were no participants with self-reported diabetes with insulin levels in the first quantile; subsequently, the first and second quantiles were combined for all analyses." (PMID 28753646, 2017). "Most cases of diabetes involve many genes, with each being a minor contributor to an intensified possibility of becoming a type 2 diabetic and similarly genes connected with T2DM poorly signify established pathways of insulin signaling." (PMID 28179884, 2017). "In summary, treatment of mouse models of diabetes with IL-1β- and TNF-antagonists, and with sodium salicylate improved insulin secretion and glycaemia to comparable levels, with an additive effect on insulin secretion with the combination of IL-1β- and TNFα-antagonists." (PMID 28740254, 2017). "Specifically, the median average insulin rate during hypothermia phase was 3.82 units/hr in patients with diabetes versus 1.89 units/hr in those without diabetes (p = 0.13)." (PMID 29075530, 2017). "The purpose of the study was to evaluate in a sample of insulin-treated diabetic patients, with type 1 or type 2 diabetes, the psychometric characteristics of the Italian version of the DEPS-R scale, a diabetes-specific self-report questionnaire used to analyze disordered eating behaviors." (PMID 28724422, 2017). "Altogether AHBA tends to be important for decreased insulin sensitivity in GDM and may be critical in the prevention and treatment of diabetes as potent biomarker." (PMID 29312952, 2017). "The Glycemia Reduction Approaches in Diabetes: A Comparative Effectiveness Study (GRADE) is an ongoing trial of 4–7 years aimed at comparing SU, insulin, DPP-4 inhibitor, and GLP-1 agonist for glycemic control and durability, which should help shed further light into the algorithm stratification." (PMID 29270438, 2017). "However, the results of the Epidemiology of Diabetes Interventions and Complications (EDIC) Study show that intensive insulin therapy delays increases in CIMT more than conventional therapy." (PMID 28724057, 2017). "Type 2 diabetes mellitus (formerly called non-insulin-dependent or adult-onset diabetes mellitus) results from the body’s ineffective use of insulin." (PMID 29295509, 2017). "Hence, it was observed that after RYGB, the expression level of diabetes-related miRNA in patients with T2DM changed to protect beta-cell function, promote glucose-induced insulin secretion, and reduce IR." (PMID 28273212, 2017). "Type 2 diabetes mellitus (T2DM) is a chronic syndrome that occurs when there is a decrease in the response of target cells towards insulin signaling (“insulin resistance”), leading to an increasing demand for insulin secretion." (PMID 29070797, 2017).
diabetes (continued). "To date, there were no reports on NEUROD1, INS, BLK and ABCC8 variants in pregnant women with diabetes." (PMID 28095440, 2017). "Among severely obese patients (BMI > 35 kg/m2) presenting for weight loss surgery, modest alcohol consumption (<200 g/week) was associated with a reduction in NASH, but the effect was not significant after controlling for diabetes or insulin resistance index." (PMID 29226116, 2017). "There are two types of diabetes: type 1 diabetes (insulin-dependent) and type 2 diabetes (non-insulin-dependent)." (PMID 28970778, 2017). "Diabetes mellitus requiring insulin treatment and diabetic ketoacidosis have not been reported in this disorder." (PMID 28588004, 2017). "Fourth, baseline fasting glucose, HbA1c, systolic pressure, diastolic pressure, serum urea nitrogen and serum creatinine levels were not very high, probably because participants’ diabetes was well-controlled without insulin treatment in the participants." (PMID 29340105, 2017). "According to the participants, postpartum diabetes screening was often not recommended to the women who did not get insulin injections and controlled their glucose levels only with their diet during pregnancy." (PMID 28451031, 2017). "Patients who took metformin had lower average degree of DNA methylation, especially in the promoter region, in all studied transporter genes compared to subjects who received insulin + metformin and subjects who did not receive any diabetes medication." (PMID 28947922, 2017). "Diabetes mellitus (DM) is a chronic metabolic disorder of various origins that begins when the pancreas fails to produce insulin in sufficient quantities or when the organism fails to respond to this hormone in an efficient manner." (PMID 27546348, 2017). "Ketone bodies, 3-hydroxybutyrate (3BOHB), and acetoacetate derive from increased free fatty acid beta-oxidation, thus reflecting marked insulin deprivation with or without decompensated diabetes." (PMID 28188583, 2017). "A recent study focused on the evaluation of the systemic effect of insulin on LPL and its regulative machinery in subjects with a different tolerance degree to insulin and showed a decrease in the adipose tissue ANGPTL4 expression in type 2 diabetes mellitus patients and healthy subjects." (PMID 28182091, 2017). "Type-2 diabetes mellitus (T2DM) is an endocrine disease related to impaired/absent insulin signaling." (PMID 28556815, 2017). "Elevated levels of fasting glucose and fasting insulin in individuals without diabetes are markers of dysregulated glucose metabolism and are strong risk factors for type 2 diabetes." (PMID 28905132, 2017). "In some of the cases, insulin was necessary shortly after the diabetes diagnosis, while in others, oral drug therapy without insulin was possible for years." (PMID 28101143, 2017). "A large number of individuals who took our initial online survey were ineligible because they did not have type 2 diabetes (n=249), were taking diabetes medications other than metformin (n=404), or had definite plans to begin taking insulin (n=35)." (PMID 28193599, 2017). "Binary logistic regression analysis showed that no baseline variable, including family history of diabetes, BMI, and indices of insulin secretion and/or sensitivity, predicted progression from NFG/NGT to IFG and/or IGT or from IFG and/or IGT to DM." (PMID 29053727, 2017). "Diabetes mellitus is a chronic disease that occurs either when the pancreas does not produce enough insulin or when the body cannot effectively use the insulin it produces." (PMID 29844777, 2017). "We observed that the levels of HOMA-IR, fasting insulin, BMI, WC, TG, TC, FBG as well as the prevalence of hypertension and diabetes stepwise increased, while serum total T, E2, SHBG, FSH and LH level stepwise declined with the increasing TyG quartiles (all P for trend < 0.01)." (PMID 29158535, 2017).
diabetes (continued). "Medications of the diabetic patients included oral anti-diabetic agents (58.8%), insulin (18.6%) or both (10.8%), while 11.8% had been receiving no diabetes treatment." (PMID 27701481, 2017). "Her insulin and C-peptide levels were also high (59 μIU/mL and 5.05 ng/mL, respectively), but she had not developed diabetes until now." (PMID 27612026, 2017). "By the study end, fasting plasma glucose insulin, and glycated hemoglobin concentrations were all markedly increased by diabetes, but not affected by therapy." (PMID 29123192, 2017). "She experienced transient complete remission of diabetes and eventually had mild diabetes with non-insulin-dependency and impaired insulin secretion." (PMID 29082260, 2017). "In analyses including all women, we found significantly more basal-like tumors (OR = 2.5(95%CI:1.09–5.74), p = 0.03) and ER-/PR-negative tumors (OR = 1.99(95%CI:1.00–3.95), p = 0.05) in non-insulin users compared to women without diabetes." (PMID 28076434, 2017). "Diabetes medication depends on the type of diabetes, as well as the severity (insulin dependent, no endogenous insulin versus insulin resistant, high levels of endogenous insulin) and duration of diabetes." (PMID 28076434, 2017). "Studies comparing insulin glargine users with human insulin users found little evidence of confounding by diabetes duration, hospitalisations or cancer screening, or by BMI, smoking, income or HbA1c levels." (PMID 28573394, 2017). "Thiazolidinediones, PPAR-γ agonists used to treat type 2 diabetes, have been shown to lower serum insulin even in normal-weight individuals without diabetes." (PMID 27586368, 2017). "Our results indicate that Fh1βKO mice eventually develop diabetes because glucose is no longer able to stimulate insulin secretion." (PMID 28954230, 2017). "Diabetes in Northern Thailand has not been extensively characterized, but is typically adult onset, not initially requiring insulin, and frequently occurring in individuals of normal BMI." (PMID 28939855, 2017). "Some patients, likely more than 50%, present in adult life without an immediate need for insulin therapy, that is with adult-onset non-insulin requiring diabetes." (PMID 28815391, 2017). "Diabetes impairs the PI3K-mediated pro-survival signalling cascade, while preserving the mitogenic Ras/MAPK-dependent pathway, thereby shifting the balance in favour of atherogenic and mitogenic actions of insulin." (PMID 28086863, 2017). "Also amongst these 10 diabetes-focused RCTs, ‘CHM plus biomedicine’ intervention was compared to ‘biomedicine’ intervention, showing a more significant decrease of insulin usage by the CHM plus biomedicine treatment after treatment." (PMID 28878815, 2017). "The disruption of IRS1 in mice retards increases in body mass and reduces insulin-stimulated glucose uptake; however, diabetes does not develop because insulin secretion increases in order to compensate for mild resistance to insulin." (PMID 28282409, 2017). "BB could stimulate glucose transport activity partly by insulin pathway and partly by AMPK activation and providing a therapeutic approach to treat diabetes." (PMID 28333970, 2017). "Data from the 2016 National Inpatient Diabetes Audit (NaDIA) of England and Wales indicated, however, only 11.5% of sites currently implement these guidelines, and that the prevalence of insulin-related medication errors has not decreased since 2011." (PMID 28852529, 2017). "Diabetes mellitus is a serious metabolic disease that results from an absolute or relative lack of insulin and chronic hyperglycemia." (PMID 28662169, 2017). "We found no compelling evidence that women with diabetes, treated with or without insulin, develop different breast cancer subtypes than women without diabetes." (PMID 28076434, 2017). "Previously, it was referred as “insulin-dependent diabetes mellitus” or “juvenile diabetes”, (ii) type-2 DM a condition in which cells does not respond to insulin." (PMID 29222671, 2017).